IL15 (interleukin 15)
Diseases named in the same sentence as IL15 in open-access papers (continued):
Sharing a sentence is not in itself a finding about the gene and the disease.
fibrosis (2 papers, 2021 to 2022). the formation of excess fibrous connective tissue in an organ or tissue in a reparative or reactive process. "Since IL-15 or IL-15/IL-15Rα treatments restrained UUO-fibrosis, we performed a semi-quantitative analysis on the cells infiltrating the kidney cortex during UUO by immunostaining using T lymphocytes (CD3) and macrophages (F4/80) markers." (PMID 34769128, 2021). "IL-15/IL-15Rα-treated UUO-kidneys presented a 22% (p < 0.05) and 40% reduction (p < 0.01, n = 7 per group) in collagen accumulation (6.48 ± 0.60% of fibrosis area) compared with IL-15-treated mice (8.3 ± 0.73% of fibrosis area) and vehicle-treated mice (10.71 ± 1.13% of fibrosis area), respectively." (PMID 34769128, 2021).
follicular lymphoma (2 papers, 2016 to 2023). Follicular lymphoma is a form of non-Hodgkin lymphoma characterized by a proliferation of B cells whose nodular structure of follicular architecture is preserved. "Also, IL-15 can cooperate with CD40L to increase growth of normal and follicular lymphoma B-cells." (PMID 27273619, 2016).
food allergy (2 papers, 2015 to 2018). Gastrointestinal disturbances, skin eruptions, or shock due to allergic reactions to allergens in food. "These effector cells, through exposure to an array of Th2 cytokines (IL-4, IL-5, IL-9, IL-13, IL-15 and IL-18) in the intestinal immune system, are primed for food allergy or anaphylactic reactions upon subsequent antigen exposure." (PMID 27840774, 2015). "These effector cells then release a collection of Th2 cytokines (IL-4, IL-5, IL-9, IL-13, IL-15 and IL-18) that are organized in the intestinal immune system for prompting food allergy or anaphylactic immune responses upon successive exposure to the antigen." (PMID 27840774, 2015).
gestational diabetes mellitus (2 papers, 2021 to 2023). "However, there is a paucity of research on the involvement of IL-15 in Gestational Diabetes Mellitus (GDM)." (PMID 33557944, 2021).
glomerulosclerosis (2 papers, 2023 to 2025). A hardening of the kidney glomerulus caused by scarring of the blood vessels. "The cytokine IL-15 promotes the formation and activation of memory CD8+T cells, which play a critical role in podocyte injury and glomerulosclerosis." (PMID 40236664, 2025).
Glucose intolerance (2 papers, 2016 to 2020). Glucose intolerance (GI) can be defined as dysglycemia that comprises both prediabetes and diabetes. "IL-15 overexpression in the skeletal muscle of diabetic zucker rats improved glucose intolerance during treadmill exercise." (PMID 28025491, 2016).
Granuloma (2 papers, 2018 to 2025). A compact, organized collection of mature mononuclear phagocytes, which may be but is not necessarily accompanied by accessory features such as necrosis. "Although there was significant heterogeneity in size of these granulomas, we found that the frequency of infected KCs that formed distinct granulomas was increased ~1.5-fold in mice pretreated with IL-15 and which had a higher number of NKT cells in the liver at the time of infection (P = 0.0038)." (PMID 29636754, 2018). "To test whether this predictive in silico data was also borne out in vivo, we treated mice for 3 days with recombinant IL-15 to induce increased NKT cell proliferation and survival and then infected these mice with L. donovani and scored early granuloma formation." (PMID 29636754, 2018).
heart failure (2 papers, 2022 to 2025). Inability of the heart to pump blood at an adequate rate to meet tissue metabolic requirements. "The levels of INF-γ, IL-12 and IL-15 were significantly higher in the saliva of heart failure subjects with both NS and HS compared to the control group." (PMID 36300113, 2022). "While IL-12p40, IL-15, and TNFα of HF participants with NT-proBNP ≥500 pg/mL were significantly higher than HF participants with NT-proBNP levels of <500 pg/mL, these cytokines do not significantly correlate with NT-proBNP levels, an indicator of heart failure progression." (PMID 41200931, 2025).
helminth infection (2 papers, 2018 to 2022). "IL-2, IL-7 and IL-15 could possibly serve as lymphoid growth factors and could underlie novel strategies for immune recovery and the optimization of immune therapies in helminth infections." (PMID 29795573, 2018). "Although little is known about the role of IL-15 in helminth infections, some studies indicated that IL-15 plays a role in the immune response against helminth parasites similar to that played in protozoan parasite infections." (PMID 36187827, 2022). "The role of CD4+ and CD8+ T cell subset distribution and the association between memory T cell subsets and the common γc cytokines (IL-2, IL-4, IL-7, IL-9 and IL-15) in helminth infections has not been explored well." (PMID 29795573, 2018). "However, the effects of helminth infection on common γc cytokine—IL-2, IL-4, IL-7, IL-9 and IL-15- levels have not been explored in Ss infection." (PMID 29795573, 2018).
Hepatomegaly (2 papers, 2016 to 2023). Abnormally increased size of the liver. "Taking together T-cell-derived IFN-γ play a prominent role in IL-15 mediated toxicityRegarding splenomegaly and hepatomegaly other cytokines induced by IL-15 like TNF-α or IL-18 might also be implicated." (PMID 27356750, 2016).
Hypercholesterolemia (2 papers, 2021 to 2024). An increased concentration of cholesterol in the blood. "Further, hypercholesterolemia induced by excess dietary cholesterol is associated with the increased serum level of IL‐15,36, 37 which potentiates the survival of TRM cells attacking melanocytes." (PMID 38421796, 2024). "It is noteworthy to stress that hypercholesterolemia leads to the upregulation of IL-15 within spleen, and blood DNA vaccination against IL-15 markedly reduces atherosclerotic lesion size but does not promote lesion stability." (PMID 34095164, 2021).
Hyperinsulinemia (2 papers, 2021 to 2023). An increased concentration of insulin in the blood. "HbA1c correlated positively with changes of MCP-2 and IL-15-RA during hyperinsulinemia (Rho ≥ 0.51) and inversely with changes of CXCL1, MMP-1 and Axin-1 during hypoglycemia (Rho ≤ -0.55)." (PMID 37400734, 2023). "Metformin and hyperinsulinemia changed the expression of extracellular proteins (e.g. metformin: CTSL, EGFR, IL5, KLK3; insulin: IL4, IL15, PGC, SORL1)." (PMID 33690729, 2021).
immunotoxicity (2 papers, 2019 to 2023). "Significant weight loss was observed after four times injections of IL-15 with a single treatment dose above 7.5 μg, which ultimately would lead to lethal immunotoxicity." (PMID 37875481, 2023). "As well, the immunotoxicity is mediated through the increased production of interleukin-15 (IL-15) by the intestinal epithelial cells and the intraepithelial lymphocytes (IEL)." (PMID 31157194, 2019).
infarction (2 papers, 2014 to 2022). A localised pathological necrosis of tissue resulting from obstruction of the blood supply usually by a thrombus, an embolus, or vascular torsion. "Our data show that some investigated parameters, such as CD15, IL-15, MCP-1, have a significantly different expression in the groups being studied (very early and older infarction)." (PMID 24989171, 2014).
infertile (2 papers, 2020 to 2025). "In contrast, miR-21 loss in eutopic glands is linked to impaired decidualization (HOXA10/IL-15 axis), with downstream infertility implications." (PMID 41226749, 2025). "Increased levels of inflammatory mediators in the endometrium of infertile patients, including IL-12, IL-15, IL-18, and IL-27, have the potential to influence uNK cell responses and to attract peripheral NK cells." (PMID 32872526, 2020).
intracerebral hemorrhage (2 papers, 2022). A cerebrovascular disorder characterized by bleeding into one or both cerebral hemispheres including the basal ganglia and the cerebral cortex. "Il-15 expression in astrocytes was significantly up-regulated in intracerebral hemorrhage (ICH) mouse models, and IL-15 predisposed microglia to an inflammatory phenotype." (PMID 35321205, 2022).
Jaundice (2 papers, 2019 to 2022). Yellow pigmentation of the skin due to bilirubin, which in turn is the result of increased bilirubin concentration in the bloodstream. "Finally, a combined panel of IL-8, IL-15 and gender demonstrated diagnostic accuracy (AUC = 0.830, p < 0.0001) in distinguishing PDAC in the presence of jaundice from benign controls with either jaundice, choledocholithiasis or common bile duct injury." (PMID 31415645, 2019).
leiomyoma (2 papers, 2021 to 2022). A well-circumscribed benign smooth muscle neoplasm characterized by the presence of spindle cells with cigar-shaped nuclei, interlacing fascicles, and a whorled pattern. "Major cytokines, namely the expression of interleukin 1 (IL1), 6 (IL6), 11 (IL11), 13 (IL13), 15 (IL15), 33 (IL33), tumor necrosis factor α (TNFα), and the granulocyte-macrophage colony-stimulating factor, have been implicated to leiomyoma pathophysiology." (PMID 34442017, 2021). "Numerous studies described leiomyoma cells exhibiting a significantly greater expression of IL1, IL4, IL5, IL6, IL10, IL11, IL13, and IL15." (PMID 34442017, 2021). "IL15 contributes to excessive ECM production, tissue remodeling and leiomyoma growth." (PMID 35740301, 2022).
liver cirrhosis (2 papers, 2023). "Our preliminary data, although obtained from a limited number of patients, identified cytokine associations, and specifically IL-5 and IL-15, potentially predictive of HCC onset in patients with decompensated liver cirrhosis." (PMID 37686245, 2023). "In the present study, we found that IL-15 expression is high in the hepatic monocytes of patients with NASH or liver cirrhosis." (PMID 37735474, 2023). "Because of the possibility of interleukin (IL) 15-mediated bystander activation of T-cell senescence, we measured IL-15 expression in liver mononuclear cells from participants with NASH and liver cirrhosis." (PMID 37735474, 2023). "We found that IL-15 expression was significantly higher in the hepatic mononuclear cells from participants with NASH or liver cirrhosis than in those from controls, but IL18 expression did not significantly differ among the three groups." (PMID 37735474, 2023).
liver failure (2 papers, 2020 to 2021). A liver disease characterized by the liver losing or has lost all of its function. "However, model experiments revealed the cytokine-related hepatotoxicity, and the data of clinical studies showed activation of NK cells and T-killers as well as fever, hypotension, and liver failure, which limits the prospects for IL-15 clinical use." (PMID 32722596, 2020).
lupus nephritis (2 papers, 2022 to 2023). Glomerulonephritis in the context of systemic lupus erythematosus. "The aim of this study was to investigate the effect of IL-15 on functional properties and associated renal damage of cytotoxic CD4 + CD28− T cell in lupus nephritis (LN)." (PMID 36320075, 2022). "A recent study on lupus nephritis provided data supporting a theory that IL-15 could be a major factor for enhancement of cytotoxic activity of CD4-positive CD28-negative T cells." (PMID 37108157, 2023). "In addition, the role of IL-15 has not been fully evaluated in local renal damage in lupus nephritis (LN)." (PMID 36320075, 2022).
medulloblastoma (2 papers, 2015 to 2022). A malignant, invasive embryonal neoplasm arising from the cerebellum. "The medulloblastoma and ependymoma cultures and tissues also secreted IL-6, IL-8 and IL-15, while the astrocytoma culture secreted no or very low levels of these interleukins." (PMID 26183281, 2015).
Miscarriage (2 papers, 2022 to 2024). A pregnancy that ends at a stage in which the fetus is incapable of surviving on its own, defined as the spontaneous loss of a fetus before the 22th week of pregnancy. "That an interleukin would be important in pregnancy establishment and maintenance is supported by studies on interleukin 1 beta (IL1B), another associated leading edge gene, and interleukin 15 (IL15), for which over-expression leads to miscarriage and implantation failure." (PMID 38927701, 2024).
myelofibrosis (2 papers, 2022 to 2025). A partial or complete replacement of the bone marrow stroma by fibrous tissue. "We identified a set of inflammatory cytokines, including IL-1alpha, IL-4, IL-6, IL-7, IL-9, IL-15 and TNF-alpha, which are elevated in the serum of JAK2V617F mice, similar to the alterations in circulating cytokines observed in patients with myelofibrosis." (PMID 40386398, 2025).
myeloid malignancies (2 papers, 2023 to 2026). "Multivariable analysis demonstrated significantly lower relapse rates with Campath compared with ATG, superior OS in myeloid malignancies, and reduced IL15-CIK efficacy in advanced disease." (PMID 41941697, 2026). "TriKE (161533) comprises two single-chain variable fragments (scFvs), one that binds to CD16 on NK cells and another that binds to CD33 on myeloid malignancies, plus an IL-15 linker bridging the CD16 and CD33 scFvs for sustained cell activation." (PMID 36830717, 2023).
neuromyelitis optica (2 papers, 2018 to 2025). A rare inflammatory disease of the central nervous system characterized mainly by attacks of uni- or bilateral optic neuritis (ON) and acute myelitis. "In experimental autoimmune encephalitis (EAE) in mice, IL-15 is upregulated and protective intrathecally and in a murine model of neuromyelitis optica, its expression in astrocytes decreases BBB permeability both for molecular compounds and for immune cells." (PMID 40003967, 2025).
NK cell leukemia (2 papers, 2022 to 2023). "In contrast, IL-15 transgenic mice develop fatal NK cell leukemia, consistent with the role of IL-15 in NK cell development." (PMID 36765626, 2023). "The IL-15-STAT5 axis has been postulated to contribute to lymphomagenesis, as IL-15 is a proinflammatory cytokine upstream of STAT5B, and transgenic mice overexpressing IL-15 develop aggressive variants of T or NK-cell leukemia." (PMID 35330161, 2022).
nonalcoholic steatohepatitis (2 papers, 2023). "Regarding TNFα signaling via NF-κB in endothelial cells, in animal studies, Pecam1 KO mouse developed nonalcoholic steatohepatitis, whereas Tlr4 KO mouse and Il15 KO mouse were protected from NAFLD." (PMID 37491046, 2023). "Besides the potential direct pro-tumorigenic effect, the association may reflect increased liver damage and inflammation in patients with a high IL-15 level, as previously observed in nonalcoholic steatohepatitis." (PMID 36831406, 2023).
oral cancer (2 papers, 2020 to 2025). "The anti-PD-L1 CAR-NK, combined with anti-PD-1 and IL-15 super antagonist N-803, enhanced NK-cell cytotoxicity in a mouse oral cancer syngeneic model, while reducing T-cell exhaustion and stimulating T-cell responses through IL-15-induced IFNγ release." (PMID 40650066, 2025). "CD44-targeted NIR-PIT combined with IL-15 treatment showed superior in vivo therapeutic efficacy to either CD44-targeted NIR-PIT or IL-15 treatment alone in colon, lung, and oral cancer models." (PMID 32927646, 2020).
plasma cell tumors (2 papers, 2012 to 2013). "The upregulation of IL-15 and IL-15Ralpha, in the B cells, suggests that this pathway is important in the pathogenesis for plasma cell tumors." (PMID 23936794, 2013). "The upregulation of both IL-15 and its receptor IL-15Ra (+1.7 fold, P = 0.045) in the B cells of p80HT mice suggest that this pathway is important in the pathogenesis of plasma cell tumors in our mouse model." (PMID 22642622, 2012). "The NF-κB2 mutant p80HT promotes the development of plasma cell tumors by transcriptional activation of genes critical for the generation, proliferation and survival of plasma cells, including cyclin D1, cyclin D2, Blimp1, survivin, IL-10 and IL-15." (PMID 22642622, 2012).
prostate (2 papers, 2011 to 2021). "In order to verify, at the systemic level our findings from BPH and localized PCA tissues, we comparatively evaluated circulating titres of IL-6, IL-7 and IL-15 in pre-operative sera from patients with prostatic diseases." (PMID 21943235, 2011).
psoriatic arthritis (2 papers, 2013 to 2019). Joint inflammation associated with psoriasis. "Patients with psoriatic arthritis have elevated expression levels of interleukin-15 and MIC in their affected synovial tissues, and this inflammatory environment enabled NK cell activation and tissue destruction through NKG2D." (PMID 30177859, 2019).
psychosis (2 papers, 2022 to 2023). "The main inflammatory factors associated with clinical outcome in psychosis were IL-15, IL-13, IL-16, and IL-8, which may be associated with poor clinical outcome." (PMID 37270510, 2023). "The main inflammatory markers associated with clinical outcome in psychosis were IL-15, IL-13, IL-16, and IL-8, which may be associated with poor clinical outcome." (PMID 35273531, 2022).
rotator cuff tear (2 papers, 2018 to 2019). "Finally, the expression of IL-15 was positively associated with severity of fibrosis and number of FAPs in patients with chronic rotator cuff tear." (PMID 30029643, 2018).
scrub typhus (2 papers, 2012 to 2022). Scrub typhus is a rare dust mite-borne infectious disease caused by the Orientia tsutsugamushi bacterium and characterized clinically by an eruptive fever which is potentially serious. "The contradictory finding of increased apoptosis and proliferation of T cells in the peripheral blood of scrub typhus patients prompted us to measure the levels of IL-7 and IL-15, which potently induce the survival and proliferation of T cells." (PMID 22905277, 2012). "To investigate the potential mechanisms of the rapid turnover and proliferation of T cells in scrub typhus patients, we measured the amount of soluble IL-7 and IL-15 in the serum of patients since these cytokines induce the proliferation of and enhance the survival of T cells in mice and humans." (PMID 22905277, 2012). "IL-15 is reported to play a pivotal role in the development, survival and function of NK cells mediated host response, and several clinical studies have demonstrated that NK cells from patients with scrub typhus contribute to enhanced intracellular bacterial killing." (PMID 35925895, 2022).
severe combined immunodeficiency (2 papers, 2022 to 2023). Severe combined immunodeficiency (SCID) comprises a group of rare monogenic primary immunodeficiency disorders characterized by a lack of functional peripheral T lymphocytes resulting in early-onset severe respiratory infections and failure to thrive. "In the spontaneous T-ALL model that we reported previously, loss of IL-15 or IL-15Rα in NOD mice with severe combined immunodeficiency (NOD.Scid) resulted in T-ALL development in all mice by 8 months of age, indicating a crucial role for IL-15 signaling in preventing leukemogenesis." (PMID 36765626, 2023). "In this study, we report a 4-month-old boy with T−B+NK− severe combined immunodeficiency (SCID) due to a novel mutation in exon 2 of IL2RG, the gene encoding the interleukin (IL) common gamma chain (γc) of the cytokine receptors for IL-2, IL-4, IL-7, IL-9, IL-15, and IL-21." (PMID 35498802, 2022).
silicosis (2 papers, 2006 to 2023). Silicosis is a respiratory disease caused by breathing in (inhaling) silica dust. "IL-15 levels were undetectable in the HC group (not shown), and for this reason, it was not further analyzed, but it was detected in the SS and PMF groups, suggesting that IL-15 was increased in ES silicosis patients." (PMID 36675056, 2023). "Pathways other than IL-12 and IL-18 appear to be driving lymphocyte activation and recruitment and IFN-γ production in silicosis, with IL-15 a likely candidate." (PMID 16396683, 2006). "The expression of IL-15 (an important driver for innate immunity, Natural Killer cell activation, and IFN-γ production) was abundant in air-exposed mice and was increased slightly in the lungs of mice with silicosis." (PMID 16396683, 2006).